CDKN2A (cyclin dependent kinase inhibitor 2A)
Diseases named in the same sentence as CDKN2A in open-access papers (continued):
Sharing a sentence is not in itself a finding about the gene and the disease.
tumor (continued). "Gain of chromosome 7, loss of chromosome 10 and homozygous deletion of the CDKN2A locus were confirmed in all analyzed tumor parts, as was the TERTp duplication and an NF1 frameshift mutation." (PMID 36114166, 2022). "As expected, somatic mutations in TERT promoter, FGFR3, and CDKN2A identified in the normal urothelium were consistently detected in tumor specimens in many cases." (PMID 36198773, 2022). "The first is represented by CDKN2A deletions, which represent both an independent mortality risk factor and one associated with midline shift and the presence of tumor residue." (PMID 36290853, 2022). "Once CDKN2A deletion or mutation occurs, it will lead to malignant cell proliferation and participate in tumor formation." (PMID 35646054, 2022). "The results showed that 10 of 12 genes were mutated in 98.23% (941/958) of tumor samples, of which CDKN2A was the most (42%)." (PMID 36713586, 2022). "Together, our results nominated CDKN2A as the cell cycle checkpoint underlying the ACTR5 network to control tumor progression." (PMID 36563143, 2022). "Sequencing data from the sensitive tumor (2R) revealed a CDKN2A homozygous loss and concomitant RB1 heterozygous loss." (PMID 36071033, 2022). "This complex SV led directly to the loss of the CDKN2A tumor suppressor signaling pathway and significantly upregulated the expression of the MIR31HG gene in its neighboring region." (PMID 35570408, 2022). "In our cohort, after adjusting for patient characteristics, treatments, and other tumor genetic alterations, we observed that while CDKN2A and CDKN2B deletions were associated with worse survival, EGFR amplification was not correlated with poor outcomes." (PMID 36380219, 2022). "CDKN2A encodes the p16 protein, a cyclin-dependent kinase inhibitor that is vital to tumor suppression and whose absence promote cell cycle progression." (PMID 35747831, 2022). "Recently, Cdkn2a null mice exposed with 4NQO developed faster and more pronounced oral lesions compared to control mice; and proliferation of tumor cells with Cdkn2a gene deletion was associated with the progression of OSCC in mice." (PMID 35154165, 2022). "One of the most well-defined functions of the tumour suppressor p14ARF, encoded by the alternative reading frame of the CDKN2a locus, is the suppression of aberrant cell growth in response to oncogenes’ activation or hyper-proliferative stimuli." (PMID 35053274, 2022). "For example, a TGGA analysis of laryngeal cancer revealed that CDKN2A has the highest mutation frequency among the top significant differential genes that IFNG significantly correlated with tumor stage and the degree of tumor differentiation." (PMID 36009223, 2022). "We observed the following aspects: CDKN2A deletions associated with midline shift presented an HR of 1.22 (p = 0.015), and CDKN2A deletions associated with the presence of residual tumor had an HR of 9.41 (p = 0.016)." (PMID 36290853, 2022). "CDKN2A gene encodes for two proteins, p16 (also known as p16INK4a) and p14arf, which act as tumor suppressors and are disabled in many types of human cancer." (PMID 35052829, 2022).
tumor (continued). "We performed a multifactorial analysis that included the main independent risk factors identified in our study (mutations or amplifications of the CDKN2A gene, midline shift, and the presence of residual tumor)." (PMID 36290853, 2022). "In conclusion, there was some crosstalk between immune ferroptosis and tumor mutations, especially CDKN2A." (PMID 36077637, 2022). "Independent factors associated with mortality were midline shift, presence of tumor residue, and CDKN2A gene deletions and amplifications." (PMID 36290853, 2022). "Part of the mechanism by which Bmi1 promotes stem cell maintenance is by negatively regulating the expression of the p16Ink4a and p19Arf tumor suppressors, both of which are encoded at the CDKN2a locus." (PMID 36167470, 2022). "Hereditary melanomas mainly develop due to mutations in the cyclin-dependent kinase 2A (CDKN2A) gene, which encodes two tumor suppressor proteins involved in the cell cycle regulation." (PMID 35465855, 2022). "We analyzed the genomic events, tumor microenvironment characteristics, and clinical outcomes associated with CDKN2A/BHD LUAD and identified a mechanism involving IFN‐I that leads to poor prognosis." (PMID 35253368, 2022). "After adjusting for patient characteristics, treatments, and tumor alterations, CDKN2A homozygous deletion was associated with worse OS (adj." (PMID 36380219, 2022). "There are two proteins, p14ARF and p16INK4A, with tumor suppressive functions encoded by the CDKN2A locus." (PMID 35004697, 2021). "In this RB1 wild-type tumor, the biallelic loss of CDKN2A was potentially targetable with CDK4/6 inhibitors." (PMID 33580196, 2021). "CDKN2A gene was mutated within a tumor that originated within the white matter of the parietal lobe, with its expression being highest within the cingulum bundle, claustrum, thalamus, and pons." (PMID 34257334, 2021). "We previously reported in another cohort that CDKN2A (p16) methylation was significantly less frequent in MSI-L colon tumours compared to MSI-H or MSS tumours and that MSI-L tumours were associated with poor survival." (PMID 34298744, 2021). "As expected because of its tumor-suppressor function, CDKN2A was altered by inactivating mutations including homozygous deletion (18/27 alterations), truncating mutation (6/27), non-truncating mutation (2/27), and SV (1/27)." (PMID 33777778, 2021). "Mutations of TTF1, MTOR, and BAI3 and deletions of CDKN2A were cross-validated to be enriched in the micropapillary tumor components using Asian and European patient cohorts." (PMID 34221970, 2021). "We found that in three of the four cases with low CDKN2A mRNA expression but strong p16 protein staining, the tumor harbors either PIK3CA mutation, PIK3CB amplification or loss of PTEN gene (case B6, NB7, NB8)." (PMID 34948172, 2021). "In case of the Cdkn2a deficient/ETV6-RUNX1 mouse model also neoplasms other than B-cell lymphomas/leukemias were developed." (PMID 35004601, 2021). "CDKN2A encodes a cell cycle inhibitor and represents a tumor suppressor gene frequently inactivated in cancers by various mechanisms." (PMID 34807923, 2021). "Given the central role of IFN I response in tumor immune surveillance, the frequent loss of all copies of IFN I genes that accompanied CDKN2A gene HD in tumor cells likely plays a role in tumor immune escape." (PMID 34249754, 2021). "In our study, we found that CDKN2A expression is negatively associated with tumor grade and ICI key genes." (PMID 35004299, 2021).
tumor (continued). "As an additional analysis, we analyzed the proportion of tumors with homozygous loss of CDKN2A/B (a clinically relevant marker in these tumors), showing a higher proportion in cluster 2 consistent with the higher overall tumor grade in this cluster." (PMID 34496929, 2021). "Next-generation sequencing identified amplification of TERT and loss of CDKN2A/CDKN2B in the primary tumor." (PMID 34127009, 2021). "To further delineate the role of the predisposing CDKN2A variant on its tumor suppressive function, we characterized cell cycle progression and proliferation of the arising grafts upon orthotopic transplantation." (PMID 34680288, 2021). "Here, we reviewed the spectrum of CDKN2A germline variants and associated neoplasms reported in literature, focusing on the relationship between distinct variant consequences on p16INK4A/p14ARF with the reported phenotypes." (PMID 33766116, 2021). "During tumor development, do these HD appear concomitantly to CDKN2A HD or do they appear later conferring an additional advantage to the tumor variant that carries them?" (PMID 34249754, 2021). "CDKN2A encodes for several transcripts: p16-INK4A and p14ARF encoding for proteins acting as tumor suppressors for different cancers." (PMID 34885058, 2021). "Inactivating mutations in FAT1 (n=3) and CDKN2A (n=3) were exclusively found in HPV-negative tumours." (PMID 34631566, 2021). "Nevertheless, a number of key tumour suppressor genes are frequently affected, including those encoding cyclin-dependent kinase inhibitor 2A (CDKN2A), BRCA1-associated protein 1 (BAP1) and neurofibromin 2 (NF2)." (PMID 34226685, 2021). "In contrast to other HGGs, deletions in CDKN2A/B, encoding the p16INK4A and p15INK4B tumour suppressors, are rare in DMGs; however, it has been shown that CDKN2A is epigenetically silenced due to the H3K27M mutation." (PMID 34944870, 2021). "CDKN2A encodes the P16 gene involved in a series of cellular pathways, including promoting tumor cell proliferation, inhibiting tumor cell apoptosis, inducing tumor stromal angiogenesis and reducing cancer cell sensitivity to chemotherapy." (PMID 34405225, 2021). "For example, it has been shown in cancer cell lines that MTAP loss (present in >99% of tumors with CDKN2A loss) results in an accumulation of the metabolite 5′-methylthioadenosine (MTA) in tumor cells and the extracellular environment." (PMID 34556668, 2021). "There is a level 4 evidence for the potential use of abemaciclib, palbociclib, and ribociclib in CDKN2A mutated tumours." (PMID 34680387, 2021). "In a study examining tumor tissues, the loss of CDKN2A function, which is regulated by gene mutations, hemizygous or homozygous loss, and promoter methylation, can be distinguished in approximately 90% of oral SCCs." (PMID 33668218, 2021). "Mutations in CDKN2A significantly reduced tumor‐free and overall survival in sarcomatoid HCC patients." (PMID 34331411, 2021). "Chromosome 9 contains a number of tumor suppressor genes, with loss of CDKN2A (9p21.3) in particular being under strong positive selection and associated with aggressive tumor growth in multiple tumor types." (PMID 33508232, 2021).
tumor (continued). "In contrast, amplification of telomerase reverse transcriptase (TERT) and loss of Cyclin Dependent Kinases Inhibitors (CDKN); CDKN2A/CDKN2B were detected in the tumor." (PMID 34127009, 2021). "Among three tumours expressed Rb1 and p16, one Rb1 positive tumour with diffuse labelling for p16 was found to have a CDKN2A mutation by NGS." (PMID 33737597, 2021). "Taken together, it appears that activation of the PI3K/AKT and Ras/Raf/MEK/ERK pathways, combined with the loss of the CDKN2A/B tumour suppressor locus, drove the growth of this tumour." (PMID 33053751, 2020). "Risk score, tumor size, CDKN2A mutation, BRCA1 mutation, N stage, residual tumor, history of radiation therapy, targeted molecular therapy, and chemotherapy were identified to be significantly related to OS of PDAC in univariate Cox analysis, with p < 0.05." (PMID 33033514, 2020). "Inactivation of CDKN2A or RASSF1A in both PDAC and GBM via promoter methylation appeared to be a common molecular event, and possibly an early event during tumor evolution, as witnessed by the loss of CDKN2A in approximately 95% of PDAC." (PMID 32183227, 2020). "The therapeutic effect was first explained by re-activation of a specific tumor-suppressor gene, such as CDKN2A, and was then shown to be associated with the suppression of tumor-initiating cells by restoration of multiple pathways in tumor cells." (PMID 32958049, 2020). "The deletion of this region usually causes co-deletion of MTAP and some classic and well-known tumor suppressor genes such as CDKN2A/B." (PMID 32093414, 2020). "Aberrant cell cycle machinery and loss of the CDKN2A tumor suppressor locus make CDK4/6 a potential target in pancreatic ductal adenocarcinoma (PDAC)." (PMID 32843618, 2020). "In this study, we established mouse LUAD cells with tumor-initiating ability driven by loss of Cdkn2a and expression of mutant KRAS or EML4-ALK oncogenes." (PMID 33348616, 2020). "P14ARF is a tumor suppressor encoded by the CDKN2a locus that is frequently inactivated in human tumors." (PMID 32698529, 2020). "ARF, encoded by the CDKN2a locus, is one of the most frequently mutated or deleted tumor suppressors in human cancer." (PMID 32759846, 2020). "The most frequent tumor suppressor gene mutation in MPM is an inactivating mutation of CDKN2A (cyclin-dependent kinase inhibitor 2A gene), which occurs in approximately 70% or more MPM cases." (PMID 33381446, 2020). "BPA increases the methylation levels of key genes associated with tumor development (e.g., BRCA1, CDKN2A, etc.), altering the epigenome in order to promote proliferation, senescence, and tumor development." (PMID 32197344, 2020). "For instance, the cell cycle gene CDKN2A isoform p16/INK4A locus often retains H3K27me3 in K27M-mutant cells, associated with decreased expression and accelerated tumor formation, though this finding is variably present." (PMID 33003625, 2020). "The alternate open reading frame (ARF) gene was originally identified as an alternative transcript of the CDKN2a locus on human chromosome 9p21 that encodes the nucleolar protein p14ARF which has a potent tumor suppressor activity." (PMID 32698529, 2020).
tumor (continued). "There was a trend towards CDKN2A copy number loss being more common in older patients (>40 years old, p = 0.020, q = 0.102) and in samples from local recurrences compared to primary tumours (p = 0.048, q = 0.154)." (PMID 31916407, 2020). "Losses at 9p21, often homozygous, were among the most common SCNAs reported, consistent with loss of the CDKN2A/B tumor suppressor locus in MPNST progression." (PMID 32642732, 2020). "A further TAA is p16 (CDKN2A), which in many cancers, is mutated, deleted, and/or minimally expressed, and therefore leads to uncontrolled cell division and tumour growth." (PMID 32942747, 2020). "CDKN2A gene encodes two proteins p16INK4a and p14arf, which are part of RB pathway, and they both inhibit mitosis by acting as tumor suppressors." (PMID 35047986, 2020). "The p16INK4a encoded by CDKN2A is a tumor suppressor and inhibits CDK4 (cyclin-dependent kinase) influencing pancreatic β cell proliferation, through decreased cell mass and subsequent decreased insulin release." (PMID 33017871, 2020). "As we transferred polyclonal Cdkn2a-loss mutant cancer cell lines, the tumours grew with slightly different dynamics." (PMID 32165639, 2020). "CDKN2A mRNA resulted in upregulation in 22.2% of HPV+ tumours, whereas HPV− tumours showed homozygous deletion and mutations in 50% and 33.3%, respectively." (PMID 32684626, 2020). "Tumor aA_7 exhibited multiple losses of chromosomal regions, homozygous deletion of CDKN2A/B and a particular mutation of BRAF (p.D594G) by NGS analysis." (PMID 32758285, 2020). "The CDKN2A locus encodes two gene products—p14ARF and p16INK4A—each under transcriptional regulation by independent promoters and each with distinct tumor suppressive functions." (PMID 32894202, 2020). "The cyclin-dependent kinase inhibitor 2A (CDKN2a) locus—frequently mutated or deleted in human cancer—encodes two different tumor suppressors, INK4a (referred to as p16INK4a) and ARF (referred to as p14ARF in humans and p19ARF in mice)." (PMID 32759846, 2020). "Noteworthy, Illumina called two additional unique CDKN2A variants (NM_001195132: c.35C > T (p.Ser12Leu) and c.35delC (p.Ser12TrpfsTer14)) in one tumor sample (ID #10), but both variants had a coverage of 108x and were thus excluded by our detection limit." (PMID 33317587, 2020). "In our study, the high expression of CDKN2A was associated with unfavorable immuno-phenotype in patients with mCRC, which is in contrast to its known role as a tumor suppressor gene." (PMID 33585439, 2020). "Copy number analysis (using methylation array data and WGS) of both the patient and PDX tumours revealed hemizygous loss of chromosome 1p and homozygous deletions on chromosome 9p including a segment containing CDKN2A/B, MTAP and multiple interferon genes." (PMID 33053751, 2020). "We showed that abnormal copy number of CDKN2A in MPM tumor cells associated with high pulmonary asbestos fiber count but not with age or MPM histologic type." (PMID 31138176, 2019). "Abnormal DNA copy number of CDKN2A in MPM tumor cells associated with patients’ high pulmonary asbestos fiber count (p = 0.044, Fisher’s Exact test, two-tailed)." (PMID 31138176, 2019). "Low-grade carcinoma usually have PIK3CA mutation and it progresses into high grade tumor after in inactivation CDKN2A." (PMID 31665050, 2019).